MTNR1A (melatonin receptor 1A)
Diseases named in the same sentence as MTNR1A in open-access papers (continued):
Sharing a sentence is not in itself a finding about the gene and the disease.
MTNR1A also shares sentences with these, for which no sentence is quoted: depression (4 papers); Obesity (3); atherosclerosis (2); lymph node metastasis (2); adolescent idiopathic scoliosis (1); allergic rhinitis (1); asthma (1); end-stage renal disease (1); glaucoma (1); Graves disease (1); Hashimoto thyroiditis (1); Horseshoe kidney (1); hypersomnia (1); infection (1); metabolic syndrome (1); neurodegenerative disease (1); non-small cell lung carcinoma (1); Parkinson's (1); prostate carcinoma (1); scoliosis (1).